ITGB7 (integrin subunit beta 7)
Diseases named in the same sentence as ITGB7 in open-access papers (continued):
Sharing a sentence is not in itself a finding about the gene and the disease.
tumor (21 papers, 2020 to 2025). "Three calpain substrates, ITGB1, ITGB3, and ITGB7, were subsequently selected for further study on the basis of their importance in tumor invasion and metastasis as well as the occurrence of missense mutations within the calpain cleavage site." (PMID 40362482, 2025). "As expected, integrins interacting with ECM components are expressed in a cell‐type‐selective fashion, such as ITGA4, ITGAL and ITGB7 by immune cells, while tumour and stromal cells strongly expressed ITGA3, ITGAV and ITGB1/4/5/6/8." (PMID 34841720, 2021). "ITGB7 also reported to express in both immune cells and tumor cells, but its study in OC was vacancy." (PMID 32765584, 2020). "Notably, targeting ITGB7 has been shown to disrupt tumor-protective interactions, enhance immune cell infiltration, and overcome immune evasion mechanisms." (PMID 40597436, 2025). "Similarly, CCR1 and ITGB7 contribute to critical tumor-stroma interactions that drive MM cell migration, adhesion, and drug resistance, emphasizing their therapeutic relevance." (PMID 40597436, 2025). "The presence of ITGB7 may indicate a more effective anti-tumor immune infiltration." (PMID 41346448, 2025). "Moreover, Foxp3UP CD8 TILs exhibited increased expression of tissue-remodeling-related genes (Mmp9) and cell-adhesion-related genes (Itgb7, Itgae, and Itgam) that may have facilitated their mobility through the tumor stroma." (PMID 36045586, 2023). "ITGB7 was expressed in both metastatic subtypes and was significantly correlated (MBM: R = 0.51, p = 1.8e-06; EM: R = 0.69, p = 1.1e-09) with the tumor ́s immune scores." (PMID 38386085, 2024). "For the cirReNET we built, there were many targeted genes involved in the mechanism of tumor genesis, such as AKT1, ErbB2, ITGB7, BAX, MAPK, FBXL12, CCL7 and so on." (PMID 35611168, 2022). "The expression of ITGB7 in SKCM TIME was positively correlated with immune cell infiltration and negatively correlated with tumor purity." (PMID 34660316, 2021). "The expression of ITGA4, ITGA8, ITGB2, ITGB7 and ITGB8 was correlated with the infiltration of all types immune cell and tumor purity in the SKCM TIME." (PMID 34660316, 2021). "Among the integrin β‐subunits, ITGB1, ITGB2, ITGB4, ITGB5, ITGB6, ITGB7, and ITGB8 were highly expressed in tumour tissues compared with normal tissues." (PMID 34709754, 2021). "The present study demonstrated that AVT inhibits MM cell proliferation in culture and impairs MM tumor growth in vivo, which is consistent with c-Maf/CCND2/ITGB7 activity." (PMID 33627137, 2021). "The migration of immune cells to tumor environment is the first step to exert their effects, therefore we selected the genes related to leukocyte migration, including IL-1β, ITGA4, ITGB2, ITGB7, CAV1, and MAG." (PMID 32358484, 2020). "By inhibiting ITGB7, this therapy aims to disrupt the interactions contributing to tumor growth and resistance mechanisms, potentially offering a novel approach for treatment-resistant MM." (PMID 40597436, 2025). "IL4I1, ITGB7, and FUT7, which were identified by comprehensive bioinformatic analysis, may play a vital role in the tumour immune microenvironment and hold the potential of enhancing ICB treatment by remodelling glucose metabolism." (PMID 34134578, 2021).
cancer (12 papers, 2015 to 2025). A tumor composed of atypical neoplastic, often pleomorphic cells that invade other tissues. "These mutations also need to be investigated given the fact that ITGB1 and ITGB7 are cancer-associated genes and are FDA-approved drug targets." (PMID 40362482, 2025). "High expression of ITGB7 has been found to be associated with poor survival of cancer cells." (PMID 29695247, 2018). "Similarly, mutations in ITGB1, ITGB3, and ITGB7 can alter their interaction with calpain, which may affect the focal adhesion of cancer cells and therefore needs to be validated further via a multidisciplinary approach." (PMID 40362482, 2025). "Other important genes in this list downregulated by TOX2-shRNA, such as ITGB7, SLAMF1, CD244, DPYSL3, KRT80 and KRT7, have been implicated in cancer progression or drug resistance." (PMID 37032358, 2023). "Surprisingly, it seems like that the more obvious the silencing of ITGB4 is, the less the migration and motility of cancer cells will be impaired, and the more obvious the silencing of ITGB7 is, the stronger the migration and movement ability of cancer cells is." (PMID 32127932, 2020). "A reduction in of ITGB7 expression might result in higher survival of cancer cells and, thus, oncogenesis." (PMID 29695247, 2018). "Most important, IL4I1, ITGB7, and FUT7 were revealed in both the cancer-immune gene set and glucose metabolic gene set." (PMID 34134578, 2021). "In conclusion, IL4I1, ITGB7, and FUT7 were identified as the hub genes between two hallmarks in cancer, glucose metabolism, and cancer-specific immunity via comprehensive bioinformatic analysis." (PMID 34134578, 2021). "However, we observed clear protein expression of ITGB7 in tumors cells at immune cell-enriched areas of Ecad+ and NGFR+ tumors, suggesting a broader function in different subtypes of metastases and cancers." (PMID 38386085, 2024). "ITGB7 is part of an integrin family and is key in interactions with cadherins and receptor molecules of ECM, which play a critical role in the pathogenesis of MM and other cancers." (PMID 36737807, 2023). "IL4I1, ITGB7, and FUT7 may be the hub genes that link glucose metabolism, and cancer-specific immunity." (PMID 34134578, 2021).
infection (4 papers, 2017 to 2023). The state of being infected such as from the introduction of a foreign agent such as serum, vaccine, antigenic substance or organism. "For example, TNFSF13B, FOS, POLR3G and PRKCE were down-regulated at 3 h post infection, while ITGB7 and THBD were up-regulated." (PMID 28938587, 2017). "However, infection of lentiviral Otub1 markedly increased c-Maf protein level and rescued the expression of ITGB7." (PMID 32999280, 2020).
cardiovascular diseases (1 paper, 2026). "Future studies should further validate the functional role of ITGB7 through animal experiments and clinical samples, evaluate the feasibility of interventions targeting this pathway, and explore its potential roles in other cardiovascular diseases." (PMID 41509664, 2026). "In addition, integrating multiomics data with clinical information to comprehensively elucidate the regulatory network of ITGB7 may provide new molecular insights and targeted strategies for the precision diagnosis and treatment of cardiovascular diseases." (PMID 41509664, 2026).
heart disease (1 paper, 2017). "Some of those genes, including ITGA4, ITGB8, MYL7, ITGB7, HIF-1α and BNP, are assosiated with heart disease pathways and are recognized as myocardial injury biomarkers." (PMID 28692647, 2017).
hematologic malignancies (1 paper, 2025). "The development of ITGB7-targeted therapies, such as OPC-415 and TRK-170, underscores the versatility of ITGB7 as a therapeutic target across a wide range of diseases, including autoimmune disorders and hematologic malignancies." (PMID 40597436, 2025).
immune system diseases (1 paper, 2023). "On the other hand, the genes ITGB7, CSAD, and TRPM2 are associated with immune system diseases that accompany skin deficiencies." (PMID 37990155, 2023).
ITGB7 also shares sentences with these, for which no sentence is quoted: acute myeloid leukemia (2 papers); leukemia (2); autoimmune disorders (1); cancers of the central nervous system (1); carcinoid (1); childhood asthma (1); colon carcinoma (1); Coronary Heart Disease (1); cutaneous melanoma (1); Ewing sarcoma (1); Familial Woolly Hair Syndrome (1); gastrointestinal stromal tumor (1); Hodgkins lymphoma (1); Hypotrichosis 13 (1); keloid (1); lymphoma (1); macrosomia (1); neuroblastoma (1); neuroendocrine carcinoma (1); non-alcoholic steatohepatitis (1); peritonitis (1); plaque psoriasis (1); prostate carcinoma (1); psoriasis (1); Salmonella Infections (1); sarcoidosis (1); T-lymphoblastic lymphoma (1); tuberculosis (1); type 1 diabetes mellitus (1); ulcerative colitis (1).
A further 1 disease shares a sentence with ITGB7 in 1 paper.